RHOA (ras homolog family member A)
Diseases named in the same sentence as RHOA in open-access papers (continued):
Sharing a sentence is not in itself a finding about the gene and the disease.
breast carcinoma (continued). "In contrast, HIF-1α transcriptional activation of RHOA has consistently been reported across a number of different cell types, including breast cancer cells, cardiac myocytes, neuroblastoma cells, mesenchymal stem cells, and chondrocytes." (PMID 35563826, 2022). "They investigated the activation of ROCK1 gene by RhoA increased TMEM16A channel activity owing to the phosphorylation of moesin at T558 in breast cancer cells." (PMID 35668455, 2022). "CuB mediates the reorganization of cytoskeletal proteins in breast cancer cells via the Rac1/Cdc42/RhoA signaling pathway, which sheds new light on the suppression of breast cancer metastasis by CuB." (PMID 36362132, 2022). "Our results demonstrate a novel reciprocal regulatory mechanism between actin modulation and SNTA1/p66Shc/RhoA signaling cascade in human metastatic breast cancer cells." (PMID 35273919, 2022). "In summary, we have demonstrated reciprocal regulation between actin modulation and SNTA1/p66Shc/RhoA signaling cascade in human metastatic breast cancer cells." (PMID 35273919, 2022). "Overall, our results manifested that RhoA/LIMK/Cofilin pathway was involved in FMNL2 silencing-induced actin cytoskeleton rearrangement in breast cancer cells." (PMID 35379791, 2022). "This was surprising since previous reports from studies performed in astrocytoma, breast cancer, colon cancer and lung cancer, showed that StarD13 depletion inhibited cancer cell migration due to the dysregulation of RhoA activation." (PMID 34958986, 2022). "Our results collectively implicate a force‐responsive program that drives an amoeboid cell state and triggers high levels of RhoA‐ROCK signaling to speed migration of a subset of breast cancer cells." (PMID 35520391, 2022). "Our previous report indicated that PROCR concomitantly activates multiple pathways including ERK, PI3K–Akt–mTOR, and RhoA–Rock–P38 signaling in breast cancer cells." (PMID 35285801, 2022). "In conclusion, FMNL2 suppressed cell migration and invasion of breast cancer by inhibiting RhoA/LIMK/Cofilin pathway through a reduction of cytoplasmic p27." (PMID 35379791, 2022). "In breast cancer, a higher concentration of statins reduces the tube-forming ability of human endothelial cells in vitro by reducing the membrane localization of RhoA, subsequently suppressing VEGFR, FAK, and Akt protein expression." (PMID 36139556, 2022). "Further, FMNL2 disrupted actin cytoskeleton rearrangement and hampered the RhoA/LIMK/Cofilin pathway in breast cancer cells." (PMID 35379791, 2022). "RhoA is required for the motility and migration of breast cancer cells, through its involvement in actin and microfilament skeleton polymerization." (PMID 36313626, 2022). "We observed that SNTA1/P66Shc/RhoA signaling downregulation altered actin organization, cell proliferation as well as decreased the migratory potential in breast cancer cells." (PMID 35273919, 2022). "miR-155 promotes this EMT process of breast cancer cells by targeting RhoA to disrupt cell tight junctions by TGF-β induction, enhancing cell migration and invasion." (PMID 35805066, 2022). "Functionally, the CD44v3 mimetic peptide impairs not only NGF-induced RhoA activation, clonogenicity, and migration/invasion of breast cancer cells in vitro but also tumor growth and metastasis in a xenograft mouse model." (PMID 35346305, 2022). "Conditioned medium from breast cancer cells (4T1) promoted MSC motility by inducing cytoskeletal changes through activation of the RhoA pathway." (PMID 35455040, 2022). "It has been shown that RhoA and RhoC are overexpressed in various cancers, including breast cancer, lung cancer, and melanoma, and are correlated with tumor metastasis." (PMID 33406809, 2021). "Collectively, these results suggested that an increase in RhoA expression is required for RKIP-mediated suppression of breast cancer cell invasion and metastasis." (PMID 34465801, 2021).
breast carcinoma (continued). "When CXCL12 expression is low, breast cancer cells promote migration via activating RhoA, while high concentrations allow the interaction between RhoA and Rac1, promoting cell–cell and cell–matrix adhesion and thus inhibiting migration." (PMID 33530455, 2021). "The analysis of our RNAseq data also showed an upregulation of the BCAR3 gene, engaged in enhanced cancer cell motility, by regulation of the balance between Rac1 and RhoA signaling in invasive breast cancer cells." (PMID 35008571, 2021). "We showed that RKIP suppressed breast cancer cells invasion and metastasis by stimulating the anti-tumor functions of RhoA." (PMID 34465801, 2021). "In an attempt to understand the intermediate signal transducers between RKIP and RhoA in regulating E-cadherin localization and breast cancer cell invasion/metastasis, we examined the effect of Erk1/2 on E-cadherin localization in BT20 cells." (PMID 34465801, 2021). "Our results therefore suggested a possible involvement of RhoA in RKIP-mediated suppression of breast cancer cell invasion." (PMID 34465801, 2021). "Overall, our study concluded that MEX3A promotes its migration and proliferation in breast cancer cells via modulating RhoA/ROCK1/LIMK1 signaling pathway." (PMID 34486491, 2021). "In summary, these data indicate that MEX3A can enhance RhoA/ROCK1/LIMK1 signaling in breast cancer cells." (PMID 34486491, 2021). "Significantly we observed a similar effect on RhoA activities upon reduction of RKIP expression in two additional human breast cancer cells." (PMID 34465801, 2021). "Here we show that RKIP increases E-cad expression through RhoA and the increased E-cad expression is the cause of RKIP-mediated inhibition of in vitro breast cancer cell invasion." (PMID 34465801, 2021). "Of note, we created crRhoA and crRhoC breast cancer cell lines and found that knocking out RhoC resulted in increased expression of RhoA while knocking out RhoA resulted in a smaller magnitude increase in RhoC expression." (PMID 34513691, 2021). "Our results show that RG combinations SF1 + TRA2B + THRAP3 and THRAP3 + RHOA + QRICH1 showed stable expression in breast cancer tissues and cell lines, respectively, and that they displayed good interchangeability." (PMID 34895237, 2021). "We previously showed that inactivation of RhoA increased breast cancer cells metastasis in a mouse orthotopic transplantation model." (PMID 34465801, 2021). "Our results showing the partial reversal of RKIP gain-of-function metastasis-suppression phenotype with a loss-of-function in RhoA indicate that RKIP interacts genetically with RhoA to regulate breast cancer metastasis." (PMID 34465801, 2021). "It has been reported that activation of RhoA increases in human breast cancer tissues depending on the stage." (PMID 33406809, 2021). "Intriguingly, as cells form intercellular contacts, ArhGEF1 is reported to redistribute to cell junctions in breast cancer cells where it stimulates RhoA activation of diaphanous to promote cortical F-actin formation." (PMID 33504879, 2021). "It is therefore possible that RKIP mitigates breast cancer metastasis partly by enhancing E-cadherin junctional localization and stabilization of adherens junctions through RhoA in primary tumors." (PMID 34465801, 2021). "We have previously shown that both RKIP and RhoA are negative regulators of breast cancer cell invasion." (PMID 34465801, 2021). "Recently, it was revealed that GPR116, a member of the poorly understood adhesion GPCR family, has a role in the invasion and migration of breast cancer cells by activating the Gαq-RhoA-Rac1 pathway." (PMID 34943797, 2021). "It was reported that in luminal type breast cancer cells, active RhoA increased E-cad localization to cell–cell contacts by activating mDia134." (PMID 34465801, 2021).
breast carcinoma (continued). "Lymph node positive luminal B tumors were enriched in pathways related to cell proliferation, immune response and cytoskeletal changes such as enrichment of PIK3CA, MAP kinases, NF-κB factors and RHOA, pathways which play role in breast cancer progression." (PMID 32947901, 2020). "On the other hand, the peptide itself determined a small but solid reduction in active RhoA in breast cancer cells." (PMID 33167372, 2020). "Pitavastatin and simvastatin have both been shown to inhibit breast cancer proliferation in vitro and in vivo by inhibiting RhoA, NF-κB, Arf6 or PI3K signaling." (PMID 32541798, 2020). "Altogether, our findings are in line with previous reports in astrocytoma and breast cancer models that uncovered the need for RhoA activation to cycle in intensity and thus allow cell migration to occur." (PMID 32900380, 2020). "As expected, invasiveness of mesenchymal transformed breast cancer cells was reduced when RhoA was activated." (PMID 33087801, 2020). "To confirm these findings, we looked at the expression of RhoA and RhoB in basal-like breast cancer tumors." (PMID 33162807, 2020). "In terms of Rho GTPase regulators, Aleskandarany and colleagues found that the expression of ARHGAP18, a RhoA-specific GAP, is associated with improved prognosis for patients with breast cancer." (PMID 32992837, 2020). "Then, Smurf1 disrupted the stability of growth-inhibitory protein RhoA by ubiquitinating and degrading RhoA, thereby promoting breast cancer cell mobility and plasticity." (PMID 33718111, 2020). "DLC1 SAM domain-binding peptides have been reported to inhibit breast cancer growth and migration through inactivation of RhoA and ROCK1 can promote migration and invasion of non small cell lung cancer by activating PTEN/PI3K/FAK pathway." (PMID 32546278, 2020). "Studies have shown that miR-31 expression correlates inversely with metastasis in breast cancer patients, which is achieved via coordinated repression of RhoA." (PMID 32315285, 2020). "At the same time, MCF-7 breast cancer cells show reduced cell–cell contact and increased migration properties after RhoA reduction, which is comparable to the suppressive effect of ARHGAP29." (PMID 33291460, 2020). "A reduction in this signaling pathway has been described in RIAM knockdown melanoma and breast carcinoma cell lines to cause impaired adhesion turnover that correlates with an inhibition of the MEK-ERK pathway and deficient RhoA activation." (PMID 32397169, 2020). "In contrast to RhoA and RhoB, research is more conclusive on the enhancing effects of RhoC on breast cancer migration and invasion." (PMID 32992837, 2020). "Our data agrees with a previous report showing that miR-182 directly targets MIM (Missing in Metastasis), which suppresses metastasis by inhibiting Ras homolog family member A (RhoA) activity and stress fiber formation in breast cancer cells." (PMID 33343622, 2020). "Depletion of BNIP-2 in MDA-MB-231 breast cancer cells decreases RhoA activity and promotes cell migration." (PMID 32789168, 2020). "We demonstrated that increased RhoA activation through decreased ARHGAP18 expression caused a decrease in cell proliferation compared with control cells that have decreased RhoA activity in breast cancer." (PMID 32992837, 2020). "Using a cohort of 106 breast tumors from the Jean Perrin hospital and data from the TCGA project, we found that a high RhoA/RhoB expression ratio was characteristic of triple negative/basal-like breast cancers." (PMID 33162807, 2020). "Beside, Arguilar-Rojas and colleagues found out that Busrelin, a GnRH agonist, regulates RhoA activity in MDA-MB-231 breast cancer cells thereby decreasing invasiveness." (PMID 33087801, 2020). "Prior studies have reported that miR-31, miR-125a-3p, miR-133a, miR-155, and miR-185 decreased RhoA expressions in osteoclasts, lung cancer cells, cardiomyocytes, breast cancer cells, and colorectal cancer cells, respectively." (PMID 32885808, 2020).
breast carcinoma (continued). "Rhosin treatment produced the same effects as RhoA siRNA in our basal-like breast cancer cell models." (PMID 33162807, 2020). "New findings show that RhoA can negatively affect the expression of chemokine receptors and thus the metastasis of breast cancer." (PMID 33291460, 2020). "Later we wanted to assess if reducing RhoA expression has an impact on invasiveness of non-invasive MCF-7 breast cancer." (PMID 33087801, 2020). "Cdc42 is inhibited by StarD13 but it remains active at sites of invadopodia, where Cdc42 is required for activating nucleation promoting factors in a similar way to the spatial regulation described for RhoA and RhoC in breast cancer cells (model)." (PMID 32900380, 2020). "TIMP knockout induces CAF-like phenotype in fibroblasts; exosomes derived from TIMPless fibroblasts are rich in ADAM10; exosome delivered ADAM10 promotes cell motility and activates Notch1 and RhoA signaling in breast cancer cells." (PMID 32957712, 2020). "We found that RhoA and PI3K are associated with ECM degradation enzyme activation and cell growth, migration, and invasion in breast cancer." (PMID 32818022, 2020). "For example, PTTG1 has been implicated in breast cancer development through regulation of the epithelial-mesenchymal transition (EMT) and functions of p27 and RhoA signaling." (PMID 33250768, 2020). "On the other hand, the peptide alone determined a small but solid reduction in active RhoA in breast cancer cells." (PMID 33167372, 2020). "Smurf1 induced degradation of RhoA promotes EGF (epidermal growth factor) induced breast cancer cell migration and invasion." (PMID 31248165, 2019). "They showed an increased activity of the small GTPase RhoA (crucial for cytoskeleton remodeling during migration and invasion) when NaVβ4 was silenced in breast cancer MDA-MB-231 cells." (PMID 30814913, 2019). "It is possible that RhoA suppresses the lung metastasis of 4T1 breast cancer cells by interfering with the access of the cancer cells to the SLN." (PMID 31705019, 2019). "Here, using a syngeneic triple negative breast cancer murine model we investigated the physiological effects of reduced RhoA expression on breast cancer tumorigenesis and metastasis." (PMID 31705019, 2019). "It remains to be determined if RhoA inhibits breast cancer cell metastasis by targeting adherens junctions, MLC2 phosphorylation, and/or focal adhesions." (PMID 31705019, 2019). "In summary, using a triple negative breast cancer mouse model, we demonstrated that reduced RhoA expression increases breast cancer lymph node and lung metastasis." (PMID 31705019, 2019). "Both inhibitors synergize to more efficiently hinder the interaction between RhoA and LARG, intensifying the reduction of breast cancer proliferation and invasion and allowing their use in the treatment of RhoA-overexpressing tumors." (PMID 30884855, 2019). "In conclusion, the present study demonstrates a previously unrecognized ROR1/cortactin/ARHGEF1-dependent pathway leading to activation of RhoA in response to Wnt5a in breast-cancer cells." (PMID 31667337, 2019). "We reasoned that if the effect of RhoA knockdown on breast cancer cell invasion is RhoA specific and physiologically relevant, we would expect to observe the opposite effect when RhoA expression or activity is increased." (PMID 31705019, 2019). "Concurring with human breast cancer cells results, reduced RhoA expression significantly increased 4T1 cells invasion through Matrigel in a dose-dependent manner." (PMID 31705019, 2019). "Overexpression of an active form of RhoA upregulates ERK1/2 in breast cancer cells and enhances motility." (PMID 30857262, 2019). "In this report we describe 2ME2 derivatives that display anti-migratory capabilities in a metastatic breast cancer cell line through their effects on the microtubule network resulting in altered focal adhesion signalling and RhoA activity." (PMID 30622437, 2019).
breast carcinoma (continued). "AGTR1 mediated cell movement and promoted lymph node metastasis by activating the FAK/RhoA pathway in early-stage breast cancer." (PMID 31781593, 2019). "The reported effects of RhoA shRNA-mediated knockdown on breast cancer cell invasion in vitro are mixed." (PMID 31705019, 2019). "Our previous work demonstrated that the Rho-GTPases are potent regulators of macrophage-induced migratory responses; therefore, we examined M2a-mediated responses in RhoA or RhoC knockout breast cancer cell models." (PMID 31214501, 2019). "Our work suggests a physiological lung and lymph node metastasis suppressor role for RhoA GTPase in breast cancer." (PMID 31705019, 2019). "Potential tumor and metastasis suppressive ability of RhoA in breast cancer have been suggested before." (PMID 31705019, 2019). "Recent studies have also proven the prognostic value of RhoA in other cancer types, such as colorectal cancer, breast cancer, and glioma." (PMID 31339860, 2019). "In this study, we investigated the role of RhoA in breast cancer cell proliferation, invasion, and metastasis." (PMID 31705019, 2019). "To investigate the possible role of RhoA in breast cancer metastasis, we exploited the well-established 4T1 syngeneic murine breast cancer model." (PMID 31705019, 2019). "We established that the proline at 841 of ROR1 was required for it to recruit cortactin and ARHGEF1, activate RhoA, and enhance breast-cancer-cell migration in vitro or development of metastases in vivo." (PMID 31667337, 2019). "To further investigate the role of RhoA in breast cancer, we stably down-regulated RhoA expression by lentiviral transduction of specific shRNAs and measured the effects of the RhoA knockdown on cancer cells proliferation and invasion." (PMID 31705019, 2019). "While we and others observed that RhoA has an anti-invasive role, published reports indicating that RhoA has a pro-invasive role in breast cancer exist." (PMID 31705019, 2019). "In breast cancer cells, reduced SCN4B expression is associated with increased RhoA activity, enhanced cell migration and invasiveness, primary tumor growth and metastatic spreading, via promoting the acquisition of an amoeboid-mesenchymal hybrid phenotype." (PMID 29723302, 2018). "We have observed previously in human breast cancer cells that Net1 controls RhoA activation and actomyosin contractility." (PMID 29769144, 2018). "Rac1, RhoA, and RhoC are commonly overexpressed in human breast cancers and RNAi-mediated knockdown or deletion of these genes inhibits tumorigenesis and metastasis." (PMID 29769144, 2018). "RhoA-directed siRNA exerted extraordinary tumor volume inhibitory effects (85% of tumor volume) in breast cancer, whereas when it was given with chitosan the tumor volume reduction was increased to 90% (to completely abolishing) for the higher dose." (PMID 29861465, 2018). "GIPC1 has anti-apoptotic effects in human breast and colorectal cancer cells, and the interaction of GIPC1 with MyoGEF, a GEF for RhoA, activates RhoA and promotes breast cancer invasion." (PMID 29659486, 2018). "Although RhoA signaling is critically important for breast cancer cell motility and invasiveness in vitro, few studies have assessed its role in metastasis in vivo." (PMID 29769144, 2018). "For example, the RhoGAP DLC-1 is deleted or epigenetically silenced in many breast cancer subtypes, driving aberrant RhoA activation and metastatic spread to the bones." (PMID 29769144, 2018). "MiR-490-3p has been reported to act as oncosuppressive microRNA to inhibit breast cancer tumorigenesis and progression by targeting RhoA directly." (PMID 30250403, 2018). "Despite evidence for RhoA and RhoC contributing to breast cancer tumorigenesis and metastasis, RhoA subfamily GEFs that contribute to breast cancer in vivo have not yet been identified." (PMID 29769144, 2018).